CD70 (CD70 molecule)
Diseases named in the same sentence as CD70 in open-access papers (continued):
Sharing a sentence is not in itself a finding about the gene and the disease.
clear cell renal cell carcinoma (8 papers, 2017 to 2025). "Likewise, it was recently described that CD70 expression is driven by hypoxia-inducible factor a in clear renal cell carcinoma." (PMID 29088768, 2017). "CD70, the ligand of CD27, is another highly promising target, especially in clear cell renal cell carcinoma (ccRCC), glioblastoma, and certain hematologic malignancies." (PMID 40624498, 2025). "AMG-172 was assessed in a phase I, first-in-human study (NCT01497821) in patients with relapsed/refractory clear cell renal cell carcinoma irrespective of CD70 expression." (PMID 40603576, 2025). "Vorsetuzumab mafodotin (SNG-75) is an IDC directed against CD70 antigen conjugated to monomethyl auristatin F (MMAF) which was tested in a phase I trial (NCT01015911) in relapsed/refractory non-Hodgkin lymphoma and metastatic clear cell renal cell carcinoma." (PMID 40603576, 2025). "Additionally, ALLO-316, an anti-CD70 CAR-T product, is being tested in the Phase 1 TRAVERSE study for patients with advanced or metastatic clear cell renal cell carcinoma (CcRCC)." (PMID 40574859, 2025). "Notably, CTX130, an allogeneic CD70-targeted CAR-T cell therapy, demonstrated promising preclinical activity and early clinical efficacy in a phase I trial involving 16 patients with relapsed/refractory clear cell renal cell carcinoma (ccRCC)." (PMID 40624498, 2025).
colorectal cancer (8 papers, 2019 to 2025). A primary or metastatic malignant neoplasm that affects the colon or rectum. "In colorectal cancer, a distinct subset of CD70‐positive CAFs has been identified, which promotes tumour progression by enhancing tumour cell migration and facilitating immune evasion through the accumulation of Tregs." (PMID 40629902, 2025). "Ongoing research aims to identify the specific cell type responsible for this interaction, drawing parallels to findings in colorectal cancer where fibroblasts were found to primarily express CD70." (PMID 40148586, 2025). "We recently discovered a subset of CD70 expressing CAFs in specimens of colorectal carcinoma patients." (PMID 34991665, 2022). "On the other hand, CD70+ CAFs are independent markers for poor prognosis in invasive colorectal cancer, they potentially increase the infiltration of Tregs and promote the immune escape of tumor cells." (PMID 34778248, 2021). "Meanwhile, the expression of CD70 on CAFs is proved to be an independent adverse prognostic marker for colorectal cancer." (PMID 31462327, 2019). "In vitro studies show CD70+ CAFs isolated from invasive colorectal cancer specimens stimulate the migration of Tregs." (PMID 31462327, 2019). "Moreover, CAFs expressing CD70 enrich regulatory T cells to invasive colorectal cancer and CD70 expression is negatively correlated with survival of patients with colorectal cancer." (PMID 33292666, 2020). "On the contrary, CD70 seems (almost) absent on the tumor cells in Kaposi sarcoma, prostate carcinoma, Langerhans cell histiocytosis and colorectal carcinoma." (PMID 34991665, 2022).
gastric cancer (8 papers, 2013 to 2025). A primary or metastatic malignant neoplasm involving the stomach. "A possible explanation is that IL-18 may have promoted gastric cancer cells migration and invasion via the regulation of CD70, CD44 and VEGF expression in immune cells, which deserves our further investigation." (PMID 24223129, 2013). "IL-18 promotes the immune escape of gastric cancer cells by upregulating programmed cell death 1 (PD1) in NK cells, downregulating CD70 in tumor cells and inhibiting the CASP8-mediated apoptosis in gastric cancer cells." (PMID 37833958, 2023). "CD27/CD70 is expressed in CD20+ B cells and CD8+ T cells in the tumor microenvironment of gastric cancer." (PMID 33575321, 2021). "Studies have shown that IL18 is highly expressed in the serum of gastric cancer patients, and endogenous IL18 can promote the metastasis of gastric cancer by enhancing the expression of CD44 and VGEF and inhibiting the expression of CD70." (PMID 36707882, 2023).
Immunodeficiency (8 papers, 2016 to 2023). Failure of the immune system to protect the body adequately from infection, due to the absence or insufficiency of some component process or substance. "While our characterization of this novel immune defect was on-going, two groups reported the association of CD70 mutations with combined immunodeficiency in a total of five patients affected by EBV-associated Hodking’s lymphoma and hypogammaglobulinemia." (PMID 29434583, 2017). "The overexpression of CD70 can be observed in different auto-immune diseases, such as rheumatoid and psoriatic arthritis." (PMID 36674828, 2023). "More recently, an autosomal recessive deficiency of CD70, the ligand of CD27, has been associated to a combined immunodeficiency with EBV-induced B-cell malignancy in humans." (PMID 29434583, 2017). "While NK cells might preferentially eliminate lytically EBV replicating cells, and immunodeficiencies that affect them could primary result in lymphoproliferations, NKT cells might be superior in restricting Hodgkin’s lymphoma and especially affected by ITK and CD70 deficiencies." (PMID 29225606, 2017). "Naive B cells from patients with common variable immunodeficiency are markedly impaired in upregulating the costimulatory molecules CD86 and CD70 upon BCR cross-linking and the expression remained reduced even in the presence of autologous helper CD4+ T cells." (PMID 28116319, 2016).
osteosarcoma (8 papers, 2015 to 2025). A usually aggressive malignant bone-forming mesenchymal neoplasm, predominantly affecting adolescents and young adults. "Next, CD70 gene expression was evaluated in diagnostic biopsies of 83 osteosarcoma patients." (PMID 25792975, 2015). "To determine whether CD70 expression on tumor cells would be associated with clinical outcome of patients with osteosarcoma, we needed to investigate CD70 expression levels in a large cohort of patients with data on follow-up." (PMID 25792975, 2015). "Preclinical studies have shown that CAR-NK cells targeting CD70 exhibit enhanced cytotoxicity against osteosarcoma cell lines, but the clinical relevance of CD70 expression in osteosarcoma patients remains to be validated." (PMID 40170852, 2025). "After machine learning by SVM-RFE and LASSO regression model, four biomarkers were chosen for the diagnostic nomogram for osteosarcoma, including ASNS, CD70, SRGN, and TRIB3." (PMID 37732314, 2023). "Our research systematically discovered and verified four immune-associated candidate hub genes (ASNS, SRGN, CD70, TRIB3) with high predictive value for diagnosing osteosarcoma by bioinformatics analysis and machine learning algorithms." (PMID 37732314, 2023). "While the OS of osteosarcoma patients with high expression of CD70 was higher than that of patients with low expression of CD70 without reaching statistical significance (p = 0.108)." (PMID 37732314, 2023). "We demonstrate that CD70 is expressed on the majority of osteosarcoma cell lines as well as patient-derived osteosarcoma cultures which were derived from CD70+ tumor tissue." (PMID 25792975, 2015). "Overall, CD70 expression tended to be more frequently detected in recurrent (2/4) and metastatic (1/3) tumors than in primary osteosarcoma tumors (1/5)." (PMID 25792975, 2015). "In a larger cohort of 83 osteosarcoma patients, a subset of tumor biopsies (19%) showed significantly higher CD70 gene expression." (PMID 25792975, 2015). "Altogether, these results indicate that CD70 protein can be expressed in primary, recurrent and metastatic osteosarcoma lesions." (PMID 25792975, 2015). "CD70 protein was expressed on most osteosarcoma cell lines (5/7) and patient-derived primary osteosarcoma cultures (4/6) as measured by flow cytometry." (PMID 25792975, 2015). "The level of CD70 expression on the primary cultures was similar to the CD70 levels on established osteosarcoma cell lines." (PMID 25792975, 2015). "Among the osteosarcoma specimens we tested, CD70 expression was heterogeneous between patients as well as within the tumor." (PMID 25792975, 2015). "CD70 expression in osteosarcoma cryosections was heterogeneous, restricted to tumor cells and not attributed to infiltrating CD3+ T cells as assessed by immunohistochemistry/immunofluorescence." (PMID 25792975, 2015). "Among pediatric bone and soft tissue cancers, we found that CD70 is preferentially expressed on osteosarcoma cells (9/13)." (PMID 25792975, 2015). "CD70 protein expression in osteosarcoma cell lines indeed correlated with CD70 mRNA expression in these cells lines (r2 = 0.87, p < 0.002)." (PMID 25792975, 2015). "Expression of CD70 was detected on five out of seven established osteosarcoma cell lines, on HOS, HOS-143b, OSA, SAOS-2 and U2OS cells but not OHS or ZK-58 cells." (PMID 25792975, 2015). "In osteosarcoma studies, CD70 has been found to be expressed in a subset of osteosarcoma patients, and CD70 may represent a novel candidate for antibody-based targeted immunotherapy in these patients with CD70 (+) osteosarcoma." (PMID 37732314, 2023). "Next, it was determined whether higher CD70 gene expression was correlated with the occurrence of metastasis, which is the most important parameter for survival of osteosarcoma patients." (PMID 25792975, 2015).
osteosarcoma (continued). "Since in particular most osteosarcoma cell lines and patient-derived primary osteosarcoma cultures exhibited high CD70 protein expression, it was examined whether CD70 was also expressed in (corresponding) osteosarcoma tumors." (PMID 25792975, 2015). "Our data illustrate that CD70 is expressed in a subset of osteosarcoma patients." (PMID 25792975, 2015). "CD70+ primary cultures were derived from CD70+ osteosarcoma lesions." (PMID 25792975, 2015). "In addition, four out of six primary osteosarcoma cultures derived from five osteosarcoma patients were positive for CD70 expression." (PMID 25792975, 2015). "CD70 gene expression in diagnostic biopsies was significantly higher in a subset of osteosarcoma patients but this difference was not correlated with metastasis-free survival." (PMID 25792975, 2015). "Moreover, CD70 was detected on few established Ewing sarcoma cell lines (5/15) at lower intensities than on osteosarcoma cell lines, while CD70 was hardly detected on neuroblastoma (1/7) and rhabdomyosarcoma (0/5) cell lines." (PMID 25792975, 2015). "CD70 gene expression in diagnostic biopsies of osteosarcoma patients did not correlate with the occurrence of metastasis and survival (n = 70)." (PMID 25792975, 2015). "Altogether, in osteosarcoma patients with CD70-postive tumors, CD70 may constitute a tumor antigen for novel targeted immunotherapy." (PMID 25792975, 2015). "Therefore, it was first investigated whether CD70 mRNA expression correlated with protein expression in osteosarcoma cell lines." (PMID 25792975, 2015). "As a result, a total of five pivotal candidate genes (ASNS, SRGN, CD70, and TRIB3) were identified for diagnosing patients with osteosarcoma." (PMID 37732314, 2023). "According to our results, ASNS, CD70, and TRIB3 were upregulated in osteosarcoma patients, while SRGN was downregulated in osteosarcoma patients." (PMID 37732314, 2023). "In this study, expression of CD70 and CD27 was analyzed in osteosarcoma cell lines and tumor specimens." (PMID 25792975, 2015). "In this study, we sought to determine the expression of CD70 and CD27 in osteosarcoma as well as other (pediatric) solid cancers, and the correlation with clinical outcome." (PMID 25792975, 2015). "The identified immune-related predictive signature, including CD70, TNFRSF9, EGFR, PDGFD and S100A6, will facilitate the development of personalized therapy for osteosarcoma and provide new insights into the role of the tumor immune microenvironment in regulating patients’ responses to chemotherapy." (PMID 34016089, 2021). "In contrast to CD70, its receptor CD27 was detected neither in CD70+ nor CD70− osteosarcoma lesions and was not expressed by infiltrating T cells (panel C and data not shown)." (PMID 25792975, 2015). "In our cohort of osteosarcoma patients, CD70 gene expression at the time of diagnosis did not correlate with metastasis-free survival, suggesting that at least in osteosarcoma, CD70 expression does not promote tumor progression." (PMID 25792975, 2015). "Moreover, CD27 was neither detected on tumor cells nor on infiltrating T cells in osteosarcoma lesions, suggesting that CD70 on tumor cells is not involved in CD27-dependent tumor-immune cell interactions." (PMID 25792975, 2015). "Since we had no access to chimeric or humanized anti-CD70 antibodies, we could not test direct or indirect cytotoxicity against CD70-expressing osteosarcoma cells." (PMID 25792975, 2015). "CD27, the receptor for CD70, was neither detected on tumor cells nor on T cells in CD70+ or CD70− tumors, suggesting that CD70 on tumor cells is not involved in CD27-dependent tumor-immune cell interactions in osteosarcoma." (PMID 25792975, 2015).
viral infection (8 papers, 2016 to 2022). "The authors proposed an association between CD70 deficiency and an increased risk of alopecia areata due to either recurrent uncontrolled viral infections or decreased proliferation and activity of T-regulatory cells." (PMID 35300124, 2022). "This also suggests that although several other T-cell co-stimulation pathways exist, such as the OX40/OX40L and 4-1BB/4-1BB-L pathways, the CD27/CD70 interaction has a unique functional role in fine-tuning T-cell-mediated immunity to virus infections." (PMID 33996677, 2021). "For example, in the presence of chronic viral infection, CD70 co-stimulation provides survival signals to antigen-activated T cells for their maintenance that ultimately leads to T cell exhaustion and defective memory immune responses." (PMID 32665635, 2020). "In models of viral infections, the accumulation and survival of virus-specific CD8+ T cells at the tissue site relied strongly on CD27/CD70 and to a lesser extent on 4-1BB and OX40 signaling." (PMID 31623665, 2019). "Several studies have shown that expression of costimulatory ligands CD40L, CD70, OX40L, and 4-1BBL on DCs overcomes T-cell tolerance and establishes superior protective immunity to tumor challenge or viral infection." (PMID 27323820, 2016). "Interestingly, the models of viral infections in CD70−/− mice showed that the lack of CD70 expression mainly affects effector CD8+ but not CD4+ nor memory T cells, supporting our conclusions that FR70 monotherapy also mainly affected the CTLs." (PMID 33737923, 2020).
kidney cancer (7 papers, 2006 to 2025). Primary or metastatic malignant neoplasm involving the kidney. "Using TSCRE, we found CD70 was regulated by a distal enhancer (‘Pair_41_CRE330’) in kidney cancer, which were further validated by FANTOME5 enhancers and pan-cancer ATAC-seq links." (PMID 38213995, 2024). "For example, CD70 is reported as a tumor-specific biomarker in kidney cancer, which promotes immune escape by inducing cytotoxic effects on B and T lymphocytes." (PMID 38213995, 2024). "We demonstrated the impact of CD70 expression on anchorage-independent growth in ovarian, lung, brain and kidney cancer cells." (PMID 29721188, 2018). "Immunohistochemistry on frozen tissue sections was used to determine expression of CD70 on a number of different types of malignant tissues including 30 kidney cancer donor tissues." (PMID 16892042, 2006). "Furthermore, exploring universal CAR-T cells represents a significant direction, exemplified by CD70 CAR-T in kidney cancer." (PMID 40969260, 2025). "Therapies targeting the CD27/CD70 axis have furthermore been shown to have some, though not dramatic, clinical effects in kidney cancer patients." (PMID 33996677, 2021). "Notably, this enhancer exhibits a significant increase in H3K27ac signal in kidney cancer compared to nonmalignant samples, which coincides with the upregulation of CD70." (PMID 38213995, 2024).
mantle cell lymphoma (7 papers, 2006 to 2024). Mantle cell lymphoma is a rare form of malignant non-Hodgkin lymphoma affecting B lymphocytes in the lymph nodes in a region called the ``mantle zone''. "Related to this case, CD70 was higher expressed on the blastoid variant of mantle cell lymphoma, a clinically more aggressive form defined by a higher mitotic rate compared to the common mantle cell lymphoma." (PMID 34991665, 2022). "Co-expression of CD70 and CD27 can be found on the surface of malignant B cells in non-Hodgkin lymphomas (NHL) such as diffuse large B cell lymphoma (DLBCL), follicular lymphoma, follicle center lymphoma, mantle cell lymphoma, Burkitt lymphoma, and Waldenström macroglobulinemia." (PMID 34991665, 2022).
multiple sclerosis (7 papers, 2020 to 2025). A progressive autoimmune disorder affecting the central nervous system resulting in demyelination. "Previous studies reported that CD70 was overexpressed on human proinflammatory Th1 and Th17 cells, which contributed to pathogenesis of multiple sclerosis." (PMID 32559178, 2020).
non-Hodgkin lymphoma (7 papers, 2010 to 2025). Distinct from Hodgkin lymphoma both morphologically and biologically, non-Hodgkin lymphoma (NHL) is characterized by the absence of Reed-Sternberg cells, can occur at any age, and usually presents as a localized or generalized lymphadenopathy associated with fever and weight loss. "This ADC was tested in a multicenter phase I dose-escalation study in patients with CD70-positive relapsed/refractory non-Hodgkin lymphoma and mRCC (NCT01015911)." (PMID 37763107, 2023). "In NK cells CD70, the ligand of the tumor necrosis factor receptor CD27, is highly expressed by non-Hodgkin lymphoma (NHL) cells." (PMID 34680190, 2021).
brain tumor (6 papers, 2006 to 2026). "CD70 is a member of the Tumor Necrosis Factor family which is highly expressed in human brain tumors and was recently shown to play an immune stimulatory role -preventing tumor growth in vivo- that encourages its application in tumor immunotherapy." (PMID 16842618, 2006). "Analysis of the cell surfaceome in pediatric and adult tumors revealed EphA3 as a prominent cell surface protein across various brain tumor subtypes, especially in the context of comparison to existing immunotherapeutic targets in clinical development EphA2, HER2, CD276, CD70, and EGFR." (PMID 39111833, 2024).
head and neck squamous cell carcinoma (6 papers, 2021 to 2025). A squamous cell carcinoma that arises from any of the following anatomic sites: lip and oral cavity, nasal cavity, paranasal sinuses, pharynx, larynx, and salivary glands. "The presence of CD70+ CAFs was also described in head and neck squamous cell carcinoma and since a role of CD70 on CAFs is still a very recent finding, it is very likely that other tumor types will follow." (PMID 34991665, 2022). "Similarly, elevated CD70 expression has been observed in CAFs and endothelial cells within head and neck squamous cell carcinoma, although the functional consequences remain insufficiently explored." (PMID 40629902, 2025). "We and others have previously uncovered a subset of CD70-expressing CAFs in colorectal cancer (CRC) and head and neck squamous cell carcinoma, and identified them as an adverse prognostic factor for CRC patients." (PMID 38331849, 2024). "Hence, CD70+ CAFs are a promising target to impede tumor migration and immune suppression in CRC and in potentially other tumor types like head and neck squamous cell carcinoma and PDAC." (PMID 38331849, 2024). "A similar trial reported favorable outcomes that CD70-specific CAR-T cells could recognize and kill CD70-positive head and neck squamous cell carcinoma cells efficiently." (PMID 35978433, 2022).